RPS6KC1 (ribosomal protein S6 kinase C1)
Description:
May be involved in transmitting sphingosine-1 phosphate (SPP)-mediated signaling into the cell. Plays a role in the recruitment of PRDX3 to early endosomes.
Synonyms: S6K-delta-1; RPK118; humS6PKh1; RSKL1; NEDSCW; S6PKh1
Tractability: PROTAC: it is named in the literature on targeted protein degradation; ubiquitination databases record sites on it; its protein half-life has been measured.
Target class: Enzyme; AGC protein kinase group; Protein Kinase; Kinase
Gene: Protein-coding gene on chromosome 1 (213,051,233 to 213,274,774, forward strand). Ensembl gene ENSG00000136643.
Subcellular location: Cytoplasm; Membrane; Early endosome
Subcellular location (Human Protein Atlas): Endosomes; Lysosomes
Gene Ontology:
Molecular function: protein binding; protein kinase activity; ATP binding; phosphatidylinositol binding
Biological process: signal transduction
Cellular component: cytoplasm; early endosome; endosome; lysosome; membrane; organelle
Genetic constraint (gnomAD): Loss-of-function variants: 32 observed, 63.1 expected, observed/expected ratio (o/e) 0.51, 90% interval 0.38 to 0.68. The upper end of that interval is the gene's LOEUF score, 0.68, which puts it in group 2 of 6, group 1 being the genes least tolerant of losing a copy. Missense variants: 907 observed, 1,057.7 expected, observed/expected ratio (o/e) 0.86, 90% interval 0.81 to 0.91. Synonymous variants: 344 observed, 378.74 expected, observed/expected ratio (o/e) 0.91, 90% interval 0.83 to 0.99.
Homologues: Orthologues: chimpanzee RPS6KC1 (99% identical), macaque RPS6KC1 (98% identical), dog RPS6KC1 (92% identical), rabbit RPS6KC1 (90% identical), pig RPS6KC1 (87% identical), guinea pig RPS6KC1 (85% identical), mouse Rps6kc1 (78% identical), rat Rps6kc1 (78% identical), tropical clawed frog rps6kc1 (57% identical), zebrafish rps6kc1 (44% identical). Paralogues in human: RPS6KL1 (19% identical), SNX15 (12% identical).
Diseases named in the same sentence as RPS6KC1 in open-access papers:
RPS6KC1 is named in the same sentence as 10 diseases in open-access papers, as found by Europe PMC text mining. Sharing a sentence is not in itself a finding about the gene and the disease. The quoted sentences say what the papers report.
Astigmatism (1 paper, 2025). A type of refraction error associated with abnormal curvatures on the anterior and/or posterior surface of the cornea. "SNPs near other loci, including RPS6KC1 rs12144639, ZC3H11B rs7525202, TRAF3IP1 rs77008212, and CASC15 rs4712652, were nominally associated with various types and components of astigmatism, as well as CR." (PMID 41320768, 2025).
benign prostatic hyperplasia (1 paper, 2025). A non-cancerous nodular enlargement of the prostate gland. "Our analysis, utilizing a pooled cohort from The Cancer Genome Atlas (TCGA), revealed that RPS6KC1 is significantly overexpressed in PCa patients compared to those with benign prostatic hyperplasia (BPH)." (PMID 40849495, 2025).
brain malformation (1 paper, 2016). "The combined variants in RPS6KC1 were identified in the proband (BAB6797) in family 025 with structural brain malformation, including cortical dysgenesis and corpus callosum abnormality." (PMID 27435318, 2016).
breast carcinoma (1 paper, 2020). "ADCK5, ETNK2, PSKH2, RPS6KC1, and SCYL3 are all significantly focally amplified in breast cancer samples as well but are not located in a peak region." (PMID 33205077, 2020).
prostate adenocarcinoma (1 paper, 2025). "Furthermore, RPS6KC1 was found to be highly expressed across multiple tumor types, including prostate adenocarcinoma (PRAD) and skin cutaneous melanoma (SKCM)." (PMID 40849495, 2025).
tumor (1 paper, 2025). "Through an integrated analysis of CRISPR genome-wide and kinome-wide screens, coupled with observations of elevated expression levels in Enz-resistant cell lines and PCa tumor tissues, our study identified RPS6KC1 as a novel essential gene implicated in Enz resistance." (PMID 40849495, 2025). "Following this, we investigated the expression of the RPS6KC1 across nine tumor cell clusters." (PMID 40849495, 2025). "Furthermore, consistent with in vitro results, RPS6KC1 knockdown significantly reduced tumor growth and size under Enz treatment compared to DMSO, especially when combined with Erastin." (PMID 40849495, 2025). "Despite the relatively small number of RPS6KC1+ cells, which resulted in a scattered dot distribution insufficient to support a violin-like pattern, significant differences in RPS6KC1 expression were observed between the nine tumor cell clusters in the PCa group and the mHSPC group." (PMID 40849495, 2025). "This study represents the first comprehensive analysis of the role of RPS6KC1 in the progression of PCa through the integration of CRISPR-based genome-wide and kinome-wide screens, scRNA-seq data from tumor tissues, and RNA-seq data from drug-resistant cells." (PMID 40849495, 2025).
RPS6KC1 also shares sentences with these, for which no sentence is quoted: Alzheimer disease (1 paper); cancer (1); prostate carcinoma (1); skin cutaneous melanoma (1).